TCEA2 (transcription elongation factor A2)
Description:
Necessary for efficient RNA polymerase II transcription elongation past template-encoded arresting sites. The arresting sites in DNA have the property of trapping a certain fraction of elongating RNA polymerases that pass through, resulting in locked ternary complexes. Cleavage of the nascent transcript by S-II allows the resumption of elongation from the new 3'-terminus.
Synonyms: TFIIS
Tractability: PROTAC: UniProt records ubiquitination sites on it; ubiquitination databases record sites on it.
Gene: Protein-coding gene on chromosome 20 (64,049,836 to 64,072,352, forward strand). Ensembl gene ENSG00000171703.
Subcellular location: Nucleus
Subcellular location (Human Protein Atlas): Nucleoplasm; Basal body; Centrosome
Gene Ontology:
Molecular function: protein binding; transcription elongation factor activity; nucleic acid binding; zinc ion binding
Biological process: DNA-templated transcription elongation; regulation of DNA-templated transcription elongation; transcription elongation by RNA polymerase II; DNA-templated transcription
Cellular component: nucleoplasm; transcription elongation factor complex; nucleus
Genetic constraint (gnomAD): Loss-of-function variants: 21 observed, 41.76 expected, observed/expected ratio (o/e) 0.5, 90% interval 0.36 to 0.72. The upper end of that interval is the gene's LOEUF score, 0.72, which puts it in group 2 of 6, group 1 being the genes least tolerant of losing a copy. Missense variants: 326 observed, 431.68 expected, observed/expected ratio (o/e) 0.76, 90% interval 0.69 to 0.83. Synonymous variants: 165 observed, 164.03 expected, observed/expected ratio (o/e) 1.01, 90% interval 0.88 to 1.14.
Homologues: Orthologues: chimpanzee TCEA2 (100% identical), macaque TCEA2 (97% identical), dog OPRL1 (94% identical), guinea pig TCEA2 (93% identical), mouse Tcea2 (89% identical), pig TCEA2 (88% identical), rat Tcea2 (84% identical), tropical clawed frog tcea3 (71% identical), zebrafish tcea2 (68% identical). Paralogues in human: TCEA1 (66% identical), TCEA3 (57% identical), TCEANC (34% identical).
Diseases named in the same sentence as TCEA2 in open-access papers:
TCEA2 is named in the same sentence as 4 diseases in open-access papers, as found by Europe PMC text mining. Sharing a sentence is not in itself a finding about the gene and the disease. The quoted sentences say what the papers report.
breast carcinoma (1 paper, 2021). "The T allele was predicted to disrupt the interaction between bta-miR-1291 with its putative target genes, increasing the protein levels of TCEA2 (transcription elongation factor A) and BCAR1 (breast cancer anti-estrogen resistance 1)." (PMID 33419037, 2021).
COVID-19 (1 paper, 2025). A disease caused by infection with severe acute respiratory syndrome coronavirus 2. "Overlapping genes for TSA and COVID-19 were SERPINH1, LPAR1, and TCEA2, and overlapping genes for TSA and MDD were NOL3, LPAR1, and HSPA6." (PMID 40918512, 2025).
TCEA2 also shares sentences with these, for which no sentence is quoted: cancer (2 papers); Hypertension (1).